VEGFA (vascular endothelial growth factor A)
Diseases named in the same sentence as VEGFA in open-access papers (continued):
Sharing a sentence is not in itself a finding about the gene and the disease.
multiple myeloma (193 papers, 2004 to 2026). "In a recent study, the number of VEGFA+ osteocytes doubled in bones bearing murine and human myeloma tumors compared to saline-injected controls." (PMID 37174109, 2023). "Downregulation of NOTCH1 signaling in mesenchymal stem cells from multiple myeloma patients leads to an elevated expression of hsa-miR-223-3p and a decrease in the VEGFA level." (PMID 34356523, 2021). "A negative correlation was observed between hsa-miR-15a-5p/hsa-miR-16-5p expression and the VEGFA level in myeloma cells." (PMID 34356523, 2021). "In this study we identified IGFBP7, a secreted factor with BMP antagonistic activity, and binding sites for IGF-1, insulin, VEGFA and activin A as a potential novel player in the pathogenesis of MM, including myeloma bone disease." (PMID 25887188, 2015). "It has recently been demonstrated that the forced expression of HOXB7 in multiple myeloma induces the up-regulation of VEGFA, FGF2, MMP2 and PDGFA, and the down-regulation of thrombospondin 2, a profile largely shared by RC." (PMID 25115389, 2014). "Myeloma cells can secrete vascular endothelial growth factor A (VEGFA) to stimulate angiogenesis." (PMID 34120619, 2021). "Moreover, MMSET is a strong co-activator of NF-κB, and their cooperation activates the expression of downstream genes, including IL-6, IL-8, VEGFA, cyclin D, Bcl-2, and survivin, to protect myeloma cells from chemotherapy-induced apoptosis." (PMID 33420361, 2021). "In multiple myeloma (MM), MALAT1 acted as ceRNA of miR-15a and miR-16 to upregulate the expression of vascular endothelial growth factor A (VEGFA), which significantly facilitated angiogenesis and led to tumor growth in a MM mouse model." (PMID 39119602, 2024). "In vitro studies showed that myeloma cells increase FGF23 in osteocytes, which in an autocrine manner upregulates osteocytic VEGFA production." (PMID 37174109, 2023). "In vivo studies using ASOs directed to lncRNAs have already achieved successful results in reducing multiple myeloma; thus, ASO targeting of VEGFA-LNC opens up new therapeutic possibilities." (PMID 33875575, 2021). "The mechanisms behind VEGFA upregulation by myeloma cells in osteocytes are not fully understood." (PMID 37174109, 2023).
retinal ischemia (188 papers, 2007 to 2026). A ischemic disease that involves the retina. "In contrast, the hallmark of PDR is the presence of retinal neovascularization driven by retinal ischemia, hypoxia, and vascular endothelial growth factor A (VEGF-A) stimulation." (PMID 38533176, 2024). "These functional alterations are followed by microvascular occlusions leading to a progressive retinal ischemia that induces the expression of the Vascular Endothelial Growth Factor-A (VEGF-A)." (PMID 34489701, 2021). "Retinal ischemia is a major contributor of neovascularization through VEGFA activation." (PMID 32599742, 2020). "However, in retinal ischemia, pro-angiogenic factors (including vascular endothelial growth factor-A, VEGF-A) induce aberrant guidance of retinal vessels into the vitreous." (PMID 20975989, 2010). "Moreover, the upregulation of some proangiogenic factors such as vascular endothelial growth factor-A (VEGF-A), leads to retinal ischemia and blood retinal barrier (BRB) impairment." (PMID 36091806, 2022).
glaucoma (179 papers, 2008 to 2026). Increased pressure in the eyeball due to obstruction of the outflow of aqueous humor. "Thus, the obtained results suggested that the increased secretion of IL8 and VEGFA proteins could be indicative of conjunctival fibrosis associated with glaucoma filtering surgery." (PMID 37569323, 2023). "Because VEGFA neutralization with bevacizumab reduced excessive scarring after glaucoma surgery, elevated protein levels of VEGFA in the AH could be a useful indicator of poor surgical outcomes in patients." (PMID 37569323, 2023). "Indeed, high levels of IL8, VEGFA, PDGF, TGFB1, and TGFA have been found in AH of glaucoma patients." (PMID 37569323, 2023). "The expression of cZBTB44, VEGFA and VCAM1 was significantly up-regulated in the AH of nAMD patients, while there was no increase in the AH of patients with age-related cataract (ARC) and glaucoma." (PMID 32194869, 2020). "Because vascular endothelial growth factor-A (VEGF-A) is a key mediator in neovascularization response, we investigated the levels of the major pro-angiogenic (VEGF-A164) and anti-angiogenic VEGF-A subtypes (VEGF-A165b) in the retina during experimental glaucoma." (PMID 18728749, 2008).
choroidal neovascularization (177 papers, 2010 to 2026). An eye disorder described by the growth of new blood vessels that originate from the choroid through a break in the Bruch membrane into the sub–retinal pigment epithelium (sub-RPE) or subretinal space. "It binds to and inhibits the biologic activity of human vascular endothelial growth factor A (VEGF-A), a molecule believed to be primarily responsible for the development of the choroidal neovascularization associated with NVAMD." (PMID 28289548, 2017). "Lucentis, also known as ranibizumab, is a humanized recombinant monoclonal antibody fragment against vascular endothelial growth factor A (VEGF-A), which can prevent choroidal neovascularization, thereby play an important role in the treatment of BRVO-induced ME." (PMID 32646391, 2020).
diabetic nephropathy (177 papers, 2008 to 2026). "Given the pivotal role of VEGFA in angiogenesis and glomerular endothelial function, genetic variations within this gene are strong candidates for influencing susceptibility to diabetic nephropathy." (PMID 41300838, 2025). "This study has several strengths, including the combined use of a case–control association study and a comprehensive meta-analysis, which together provide robust insights into the contribution of VEGFA variants to diabetic nephropathy (DN)." (PMID 41300838, 2025). "Decreased pro-angiogenic factor vascular endothelial growth factor A (VEGFA) can cause glomerular microangiopathic and lead to the onset of pre-eclampsia, whereas upregulated VEGFA plays a protective role in diabetic nephropathy and polycystic nephropathy." (PMID 37266443, 2023). "VEGFA is an important regulator of angiogenesis and vascular permeability with a possible pathogenic role in diabetic nephropathy." (PMID 33178322, 2020). "More specifically, high BB-DNA levels could be considered a biomarker of diabetic nephropathy, as they have been associated with increased methylation levels of VEGFA and NMNAT1, key contributors to the progression of diabetic kidney disease." (PMID 40724814, 2025). "Down-regulation of CTGF and vascular endothelial growth factor-A (VEGF-A) in diabetic nephropathy is speculated to be a result of podocyte loss." (PMID 25973922, 2015). "Additionally, variation in VEGFA has been associated with diabetic nephropathy." (PMID 30862128, 2019). "The secretion of vasohibin by GEnCs in turn protects podocytes by counteracting VEGFA signaling in situations of pathologically increased VEGFA levels such as were observed in diabetic nephropathy." (PMID 40698593, 2025). "Previous research has reported low VEGFA expression in the renal tubulointerstitial compartment of diabetic nephropathy (DN) patients." (PMID 40369957, 2025). "Using bioinformatics tools, FF has been previously predicted to increase VEGFA expression in diabetic nephropathy, while the drug has been shown to increase VEGFA levels in the visceral adipose tissue of FF-treated normolipemic rabbits." (PMID 38474282, 2024). "VEGFA has been widely acknowledged as a promoter of angiogenesis, which enhances permeability and fosters the progression of diabetic nephropathy." (PMID 37415174, 2023). "Clinical studies have shown that in the early stages of diabetic nephropathy, VEGFA levels are elevated in the urinary vessels of diabetic patients." (PMID 37404805, 2023). "Appropriate amounts of VEGFA are beneficial for maintaining glomerular structure, while excessive VEGFA leads to abnormal angiogenesis and is involved in renal fibrosis in diabetic nephropathy." (PMID 37511521, 2023). "TCF7L2 is a key transcriptional effector molecule of the Wnt signalling pathway, which can affect diabetic nephropathy by regulating the expression of VEGFA." (PMID 35846885, 2022). "In diabetic nephropathy, VEGFA is involved in VEGF/nephrin pathway, VEGF/nitric oxide synthase pathway, insulin resistance and angiopoietin expression." (PMID 33987885, 2021). "In conclusion, the blockade of VEGFA can effectively restore renal function in diabetic nephropathy." (PMID 33178322, 2020). "High expression of VEGFA can make a contribution to the development of diabetic nephropathy and other glomerular diseases." (PMID 26061387, 2015). "We found a decreased vascular endothelial growth factor A transcription in both mouse strains at an early stage of diabetic kidney disease." (PMID 22645604, 2012). "Vascular endothelial growth factor A (VEGF-A), a proinflammatory growth factor and regulator of angiogenesis and vascular permeability, has been reported to have increased expression in diabetic nephropathy, associated with increased glomerular permeability and proteinuria." (PMID 39996798, 2025).
diabetic nephropathy (continued). "In addition to being directly related to T2DM, the polymorphisms of VEGFA, EGFR, PTGS2, and AKT1 genes are mainly related to diabetic vascular dysfunction and play an important role in diabetic vascular disease and diabetic nephropathy." (PMID 33134394, 2020). "Increased expression of VEGFA in glomeruli was also detected in minimal change of disease, membranous nephropathy, mesangial proliferative glomerulonephritis, lupus nephritis, and diabetic nephropathy." (PMID 26274923, 2015). "For example, podocyte-secreted vascular endothelial growth factor-A (VEGF-A) is required for maintaining the normal GEC function and the alteration of its signaling pathway leads to thrombotic microangiopathy and is implicated in diabetic nephropathy pathogenesis." (PMID 34244474, 2021). "In this study, GHR, VEGFA and EFEMP1 were identified as potential biomarkers for diagnosing and treating diabetic nephropathy." (PMID 37404805, 2023). "Vascular endothelial growth factor-A (VEGF-A) and nitric oxide (NO) are essential for glomerular filtration barrier homeostasis, and both are disregulated in diabetic nephropathy." (PMID 35280251, 2021). "Vascular endothelial growth factor A (VEGF-A) and P2-receptors (P2Rs) are involved in the pathogenesis of diabetic nephropathy." (PMID 33635529, 2021). "Vascular endothelial growth factor-a (VEGF-A) and nitric oxide (NO) are essential for glomerular filtration barrier homeostasis, and are dysregulated in diabetic kidney disease (DKD)." (PMID 35280251, 2021).
psoriasis (166 papers, 2005 to 2026). An autoimmune condition characterized by red, well-delineated plaques with silvery scales that are usually on the extensor surfaces and scalp. "For instance, VEGFA is associated with psoriasis, adenocarcinoma, and Alzheimer’s disease, suggesting a link between angiogenesis, inflammatory responses, and neurodegeneration." (PMID 39337647, 2024). "A genetic variant in VEGFA is also associated with more severe psoriasis (+405 CC) and is thought to result in increased VEGF-A production." (PMID 29535706, 2018). "Taken together, we indicated miR-150 regulates human keratinocytes’ proliferation in hypoxic conditions through targeting HIF-1α and VEGFA in psoriasis for the first time, and provide diagnostic markers and a potential novel target for psoriasis treatment." (PMID 28399173, 2017). "Taken together, we indicated miR-150 regulates human keratinocytes’ proliferation in hypoxic conditions through targeting HIF-1α and VEGFA in psoriasis for the first time, and provide diagnostic markers and a novel target for psoriasis treatment." (PMID 28399173, 2017). "Vascular endothelial growth factor A (VEGF‐A)‐mediated angiogenesis is central to the pathogenesis of psoriasis." (PMID 39624732, 2024). "Vascular endothelial growth factor A (VEGF‐A)‐mediated angiogenesis is involved in the pathogenesis of psoriasis." (PMID 39624732, 2024). "This case control study explored the effect of psoriasis on the gingival crevicular fluid (GCF) levels of vascular endothelial growth factor A (VEGF-A) in patients with different stages of periodontitis." (PMID 39512356, 2024). "We report that vascular endothelial growth factor‐A (VEGF‐A) inhibition downregulates inflammatory angiogenesis in psoriasis plaque skin ex vivo." (PMID 37799359, 2023). "The VEGFA gene is located at the PSORS1 locus, which is highly polymorphic and associated with psoriasis severity." (PMID 35075118, 2022). "Keratinocyte-specific deletion of Flt1 or Nrp1 diminished VEGFA-induced psoriasis, suggesting that VEGFA/Flt1/Nrp1 axis has an essential epidermal autonomous function in the pathogenesis of psoriasis." (PMID 35075118, 2022). "The keratin 14 (K14)-vascular endothelial growth factor A (VEGF-A)-transgenic mouse model, a psoriasis animal model that overexpresses VEGF in the epidermis, can spontaneously develop a chronic inflammatory skin disease similar to human psoriasis." (PMID 35495722, 2022). "Vascular endothelial growth factor A (VEGF‐A), a mediator of inflammatory angiogenesis in psoriasis, plays a major role in its pathogenesis." (PMID 35851722, 2022). "Altogether, these results indicate the epidermal VEGFA signaling as a promising therapeutic target for psoriasis." (PMID 35075118, 2022). "Growth factors and their receptors such as VEGFA, EGF, and EGFR were also inextricably linked with psoriasis." (PMID 35265149, 2022). "In addition, the VEGFA gene is located in close vicinity of PSORS1 at the psoriasis susceptibility locus on chromosome six at 6p21 and the +405 CC “high VEGF-A-producing genotype” is associated with early onset of psoriasis, suggesting that a pro-angiogenic factor may influence disease progression." (PMID 31357710, 2019). "The VEGFA gene is located on chromosome 6 at 6p21, close to PSORS 1, which is a known chromosomal locus for psoriasis susceptibility." (PMID 29535706, 2018). "Results from qPCR assays showed that both HIF-1α and VEGFA mRNA was up-regulated in psoriasis tissues." (PMID 28399173, 2017). "Taken together, we demonstrate that the expression of miR-150 is significantly down-regulated in lesional psoriatic skin, and is specifically related to HIF-1α and VEGFA during the psoriasis process." (PMID 28399173, 2017). "During the psoriasis process, proliferating keratinocytes exhibit hypoxia-induced VEGFA expression, which initiates a process that aims to achieve the proper flow of blood through the lesional skin." (PMID 28399173, 2017).
psoriasis (continued). "These inspired us to presume that miR-150 might regulate HIF-1α and VEGFA to modulate human keratinocytes proliferation in psoriasis." (PMID 28399173, 2017). "Besides, HIF-1α and VEGFA were reported as crucial regulators during the pathogenesis of psoriasis." (PMID 28399173, 2017). "Excessive proliferation of keratinocytes in psoriasis causes local environmental hypoxia, leading to increased expression of HIF-1α; microenvironment hypoxia accelerates vascular growth to supply the oxygen required for cell growth, along with the elevated expression of VEGFA during this process." (PMID 28399173, 2017). "VEGFA was decreased post-NB-UVB treatment, which has been similarly seen to be decreased by light therapy and in psoriasis patients after NB-UVB therapy." (PMID 40475059, 2025). "Angiogenesis is predominately mediated by vascular endothelial growth factor A (VEGF‐A), which is overexpressed in the skin and plasma of patients with psoriasis." (PMID 39624732, 2024). "Vascular endothelial growth factor A (VEGFA), the main epidermal-derived vessel-specific growth factor, is overexpressed in several inflammatory diseases, including psoriasis." (PMID 35075118, 2022). "By restoring the physiological process of KCs proliferation and differentiation and reducing the expression of vascular endothelial growth factor A (VEGF-A), IL-38 remarkably alleviated the severity of psoriasis like phenotype induced by imiquimod (IMQ)." (PMID 34539413, 2021). "In a mouse model of psoriasis, conditional deletion of VEGFR1 or neuropilin 1 (a VEGFA co-receptor amplifying VEGFA signaling in epidermal cells) inhibits psoriasis triggered by VEGF-A overexpression." (PMID 34769465, 2021). "These indicated that in psoriasis cells, miR-150 inhibits the cell proliferation induced by hypoxia, as well as the accelerated expression of HIF-1α and VEGFA." (PMID 28399173, 2017). "Besides, miR-150 regulates HIF-1α and VEGFA by direct binding to the 3’UTR of HIF-1α and VEGFA to inhibit human keratinocytes’ proliferation, suggesting that miR-150, HIF-1α and VEGFA may serve as useful diagnostic markers and novel targets for treatment strategies of psoriasis." (PMID 28399173, 2017).
type 2 diabetes (158 papers, 2008 to 2026). "In a large case–control study among Han Chinese type 2 diabetic patients, VEGFA rs2010963 and rs69947 variants were linked to increased DN susceptibility." (PMID 41300838, 2025). "Several miRNAs are potential markers of type 2 diabetes by targeting factors such as vascular endothelial growth factor A (VEGFA), which is known to underlie the risk of type 2 diabetes." (PMID 37833930, 2023). "After determination of the risk alleles for these associations, only the risk allele of the ADAMTS9 SNP rs4607103 and the risk allele of the VEGFA SNP rs9472138 were identical with the recently reported risk alleles for type 2 diabetes." (PMID 18714373, 2008). "Many loci associated with adiponectin levels are shared with other insulin resistance traits and risk of type 2 diabetes, including loci near IRS1, LYPAL1, ARL15/FST, VEGFA, CMIP, and PEPD." (PMID 32915782, 2020). "We have previously confirmed the associations of genetic variants in HHEX, CDKAL1, VEGFA and FTO with type 2 diabetes in Han Chinese." (PMID 25587982, 2015). "Interestingly, after network construction, we also found that active ingredients can play a therapeutic role in type 2 diabetes by activating the VEGFA to regulate the expression of PI3R1 and decreasing insulin resistance." (PMID 32265717, 2020). "We further evaluated the cumulative effect on type 2 diabetes of these 4 SNPs, in combination with 5 SNPs at HHEX, CDKAL1, VEGFA and FTO reported previously." (PMID 25587982, 2015). "The seven loci shed new light on regions containing genes with a reported role for type 2 diabetes (PPARG, ADAMTS9, VEGFA), lipids (GRB14, MAP3K1) and hormone metabolism (HSD17B4)." (PMID 23754948, 2013).